SMC4 (structural maintenance of chromosomes 4)
Diseases named in the same sentence as SMC4 in open-access papers (continued):
Sharing a sentence is not in itself a finding about the gene and the disease.
prostate carcinoma (continued). "Notably, the elevated expression levels of SMC4 demonstrate a noteworthy correlation with overall patient survival, thus rendering it a potentially valuable prognostic marker for prostate cancer." (PMID 40278414, 2025). "Thus, SMC4 potentially regulates the growth and metastasis of metastatic prostate cancer cells through the Rheb/mTOR pathway." (PMID 40278414, 2025). "Thus, SMC4 knockdown can effectively suppress metastatic prostate cancer cells’ growth, migratory, and invasion capabilities." (PMID 40278414, 2025). "Elevated levels of SMC4 may potentially serve as a prognostic biomarker in prostate cancer." (PMID 40278414, 2025). "Furthermore, we explored the mechanism by which SMC4 promotes prostate cancer cell metastasis." (PMID 40278414, 2025). "Therefore, to determine the functional effect of SMC4 on metastatic prostate cancer cells, we knocked down SMC4 in RM1‐LM cells and demonstrated that SMC4 knockdown notably inhibited cellular proliferation, migration, and invasion in vitro and affected cell cycle." (PMID 40278414, 2025). "Collectively, the data suggests that the interaction between SMC4 and GLUT1, as confirmed by co‐IP, promotes prostate cancer cell metastasis through the Rheb/mTOR pathway." (PMID 40278414, 2025). "After constructing the prognostic prediction model, SLPI, VSIG2, CENPF, SLC7A1, SMC4, and ITPR2 were finally regarded as the key genes in the prognosis of patients with prostate cancer." (PMID 36937411, 2023). "Even the combination of the five genes, including LARP4B, PLEKHF2, SMC4, SLC45A3 and NO6632,39,44,45,48,51, whose clinical relevance and prognostic implications were observed in prostate cancer, had very limited prediction strength for BCR and RFS (not reported in the Results section)." (PMID 35732666, 2022).
lung carcinoma (8 papers, 2016 to 2025). "In our study, we first found a connection between SMC4 and lung cancer, but the underlying specific molecular mechanism and the potential use of SMC4 as a prognostic marker in lung ADC require further investigation." (PMID 27687868, 2016). "In summary, SMC6, CDC27, CDC7, RACGAP1, SMC4, NCF1,2,4, SELPLG and CFP are significantly associated with T2DM and lung cancer, making them potential target genes for disease prediction and treatment in the future." (PMID 38468345, 2024). "From the Clinical Proteomic Tumor Analysis Consortium (CPTAC) database, we observed that the lung cancer tumor tissues exhibited a significantly higher level of SMC4 protein than that in the normal tissues (p < 0.001)." (PMID 37007153, 2023). "The overexpression of SMC4 can promote the proliferation of lung cancer cells and serves as an independent prognostic factor for lung cancer." (PMID 35372377, 2022). "In the Cox regression model, univariate Cox regression indicates that the T stage (p < 0.05), N stage (p < 0.001), M stage (p < 0.001), SMC4 (p = 0.049), pathologic stage (p < 0.001), residual tumor (p < 0.001) and Age (p = 0.022) were correlated with the lousy prognosis of lung cancer." (PMID 37007153, 2023). "In the study on the relationship between SMC4 and non-small cell lung cancer, Nie H also confirmed that SMC4 was highly expressed in lung cancer cells and tissues by quantitative reverse-transcription polymerase chain reaction (QRT-PCR), WB, and plasmid transfection." (PMID 37007153, 2023). "Downregulated expression of SMC1A, SMC3, and SMC4 could induce growth suppression in lung cancer cells via G1/S cell cycle phase arrest and the apoptosis pathway." (PMID 34336829, 2021). "In conclusion, the pivotal role of SMC4 in lung development and carcinogenesis suggests that genes with a similar expression pattern to SMC4 in lung development may also contribute to lung cancer progression." (PMID 27687868, 2016). "Furthermore, SMC4 gene knockout can significantly inhibit the proliferation and invasion of A549 cells; therefore, SMC4 may also be a potential biomarker of lung cancer and help to clarify its carcinogenic mechanism." (PMID 37007153, 2023). "In the Cox regression model, univariate Cox regression indicates that the Age (p < 0.001), N stage (p < 0.001), M stage (p < 0.001), SMC4 (p = 0.036), pathologic stage (p < 0.001), menopause status (p < 0.001) and radiation therapy (p = 0.004) were correlated with the lousy prognosis of lung cancer." (PMID 37007153, 2023). "Bioinformatics analysis manifested that the unpaired (p < 0.001) and paired (p < 0.001) differential expression analyses between normal and lung cancer groups indicated that SMC4 was expressed significantly higher in tumors compared to normal tissue." (PMID 37007153, 2023). "We ultimately selected SMC4, which has not yet been studied in lung cancer, for further exploration." (PMID 27687868, 2016). "There is no research on SMC4 and SMC6 in lung cancer and diabetes, which needs further exploration." (PMID 38468345, 2024).
lung adenocarcinoma (7 papers, 2013 to 2025). A carcinoma that arises from the lung and is characterized by the presence of malignant glandular epithelial cells. "The risk of lung adenocarcinoma-related death in patients with high SMC4 expression was about 1.5-fold that of those with lower expression." (PMID 33460400, 2020). "Interestingly, a study previously reported that DDX46 interacts with SMC4, which was identified substantially involved in lung development and highly related with the progression of lung adenocarcinoma." (PMID 34573320, 2021). "Strong expression of SMC4 was also significantly related to the poor OS of patients with lung adenocarcinoma, indicating that it might be an independent poor prognostic factor for this tumor." (PMID 33460400, 2020). "SMC4 silencing inhibits the proliferation and invasion of lung adenocarcinoma cells." (PMID 29467813, 2018). "Moreover, SMC4 is overexpressed in lung adenocarcinoma tissues and acts as an independent prognostic predictor." (PMID 29467813, 2018). "Moreover, SMC4 is overexpressed in lung adenocarcinoma tissues and acts as an independent prognostic factor." (PMID 27687868, 2016).
colon cancer (4 papers, 2020 to 2025). "Recent studies have shown that SMC4 is aberrantly expressed in HCC and colon cancer." (PMID 38468345, 2024).
lymphoma (4 papers, 2009 to 2023). A malignant (clonal) proliferation of B- lymphocytes or T- lymphocytes which involves the lymph nodes, bone marrow and/or extranodal sites. "In patients with pyothorax-associated lymphoma, loss-of-function mutations in SMC2 and SMC4 are associated with abnormal mitosis and genomic instability." (PMID 35916925, 2022).
cervical cancer (3 papers, 2013 to 2023). A primary or metastatic malignant neoplasm involving the cervix. "In the Cox regression model, univariate Cox regression indicates that the T stage (p = 0.025), N stage (p = 0.002), M stage (p = 0.023), and SMC4 (p = 0.043) were correlated with the bad prognosis of cervical cancer." (PMID 37007153, 2023). "In vitro, cytological studies also demonstrated that SMC4 overexpression facilitated the development of cervical cancer cells by activating NF-κB pathway, which provides a new therapeutic target for patients with cervical cancer." (PMID 37007153, 2023). "Moreover, further research by protein-protein interaction network analysis showed that SMC4 was closely associated with MELK and TTK, which were promising candidate markers for cervical cancer prognosis and also emerged as potential therapeutic drug targets." (PMID 37007153, 2023). "The results show that SMC4 may be recognized as one hub gene with the highest connectivity degrees and be suggested to play crucial roles in the development of HPV-positive cervical cancer." (PMID 37007153, 2023).
glioblastoma (3 papers, 2018 to 2025). The most malignant astrocytic tumor (WHO grade IV). "We investigated the role of SMC4, a key gene in the disulfidptosis-Tex-related prognostic model, in the migratory behavior of glioblastoma cells." (PMID 39949776, 2025). "In the Oncomine database, we observed the elevated expression of SMC4 in different cancer types and different glioblastoma databases." (PMID 34868977, 2021). "Future studies should delve deeper into the roles of these genes in disulfidptosis-Tex and glioblastoma progression, investigating the precise molecular mechanisms by which SMC4 operates and its interplay with immune cells, to fully elucidate their mechanisms and therapeutic potential." (PMID 39949776, 2025). "The qRT-PCR results confirmed the down-regulation of the mitotic cell cycle regulators such as CDK2 and SMC4 in both lung and glioblastoma SOX2OT knocked down cancer cell lines, while the CDK2AP2 which is also known to interact and inhibit CDK2, is up-regulated more than two times in treated cells." (PMID 30202240, 2018).
gastric cancer (2 papers, 2020 to 2023). A primary or metastatic malignant neoplasm involving the stomach. "In contrast, a higher expression level of SMC4 predicted a better prognosis of Gastric Cancer (OS: HR = 0.71, P = 9.8e-05; PPS: HR = 0.56, P = 3.4e-07)." (PMID 36719264, 2023). "There was also evidence indicating the transcription of SMC4 was activated by NF-κB through regulation of miR-16 and miR-21 in gastric cancer, and SMC4 could participate in chronic lymphocytic leukemia (CLL) with post-transcriptional regulation of miR-15/− 16 family members." (PMID 32586319, 2020).
leukemia (2 papers, 2023 to 2025). A malignant (clonal) hematologic disorder, involving hematopoietic stem cells and characterized by the presence of primitive or atypical myeloid or lymphoid cells in the bone marrow and the blood. "Knockout of SMC4 expression can reduce the proportion of leukemia stem cell (LSC) and then affect its ability to start leukemia." (PMID 37007153, 2023). "For fludarabine, SMC4 associated with the outcome of pediatric acute lymphoblastic leukemia, and TNFRSF13C and HLA-DQB1 for which specific gene variants had been associated with different types of leukemia were included." (PMID 41146244, 2025). "It further revealed that SMC4 played a vital role in the progression of AML and provided new insights into the maintenance mechanism of leukemia stem cells." (PMID 37007153, 2023).
sarcoma (2 papers, 2020 to 2023). A usually aggressive malignant neoplasm of the soft tissue or bone. "The GEPIA and TIMER datasets were adopted to investigate the associations between SMC4 and prognosis in various cancers, especially in sarcoma." (PMID 36719264, 2023). "Previous studies have also reported that expression of SMC4 was significantly higher in lung adenocarcinoma, a type of sarcoma, and was significantly associated with a higher mortality rate." (PMID 36719264, 2023). "The association between SMC4 and immune cell infiltration in 39 cancer types, including sarcoma was analyzed using the TIMER dataset." (PMID 36719264, 2023). "This study showed an important association between SMC4 and the prognosis of sarcoma and other cancers." (PMID 36719264, 2023). "The relationship of SMC4 with immune cell infiltration was analyzed in sarcoma, which indicated that SMC4 expression was associated with the infiltration status of immune cells in sarcoma." (PMID 36719264, 2023). "Additionally, we further studied the association of SMC4 with tumor-infiltrating immune cells in sarcoma tissues." (PMID 36719264, 2023). "SMC4 was found to be significantly related to poorer OS in sarcoma patients with reduced eosinophils, CD8+ T-cells, CD4+ memory T cells, B cells, basophils, natural killer T-cells, regulatory T-cells and type 2 T-helper cells." (PMID 36719264, 2023). "Our research also indicated that SMC4 was connected to the degree of immune cell infiltration in a variety of tumors, including sarcoma." (PMID 36719264, 2023). "According to the results from our study, SMC4 has a potential to serve as a biomarker for the evaluation of the immune cell infiltration and prognosis of sarcoma." (PMID 36719264, 2023). "In summary, our study suggested that SMC4 is related to the immune cell infiltration in sarcoma tissues and can predict the prognosis of pan-cancer." (PMID 36719264, 2023). "In sarcoma, the expression of SMC4 was correlated with the infiltration of B cells and CD8+ T cells but negatively correlated with the immune infiltration of CD4+ T cells and macrophages." (PMID 36719264, 2023). "To this end, we have conducted this study with the aim to show the prognostic significance of SMC4 in sarcoma and its interaction with infiltrating immune cells." (PMID 36719264, 2023). "GEPIA and TIMER databases were used to discover the relationships of SMC4 with immune cell infiltration in sarcoma." (PMID 36719264, 2023). "Under different immune cell infiltration conditions, SMC4 has different prognostic significance for sarcoma." (PMID 36719264, 2023). "Meanwhile, we observed that expression of SMC4 was positively related to sarcoma patients with enriched basophils, type 1 T-helper cells, macrophages, mesenchymal stem cells, type 2 T-helper cells and regulatory T-cells." (PMID 36719264, 2023). "Correlation of SMC4 mRNA expression and overall survival rate in sarcoma with different immune cells by Kaplan-Meier plotter." (PMID 36719264, 2023). "Our study also shows that the lower expression of SMC4 is related to a poorer prognosis of sarcoma and more infiltration of various immune cells, including B cells, neutrophils monocytes, NK cells and macrophages." (PMID 36719264, 2023). "Specifically, in sarcoma, the expression level of SMC4 is significantly correlated with monocyte markers CD14 and CSF1R, TAM marker CD80, and M1 macrophage marker PTGS2." (PMID 36719264, 2023). "In the present study, SMC4 was found to be highly expressed in sarcomas and human sarcoma cell lines." (PMID 33460400, 2020). "Therefore, we analyzed the DEGs between the SMC4 high group and the SMC4 low group using data on sarcoma from TCGA." (PMID 36719264, 2023). "For the sarcomas, the expression level of SMC4 was related to the infiltration levels of B cells (r = 0.182, P = 4.65e-03) and CD8+T cells (r = 0.186, P = 3.91e-03), negatively related to the infiltration levels of CD4+ T cell (r = −0.218, P = 7.00e-04) and macrophage (r = −0.14, P = 3.18e-02)." (PMID 36719264, 2023).
sarcoma (continued). "Therefore, SMC4 has the potential to serve as a biomarker for the evaluation of the immune cell infiltration and prognosis of sarcoma." (PMID 36719264, 2023). "SMC4 may affect the prognosis of patients with sarcoma by regulating tumor immune function." (PMID 36719264, 2023). "Many pathways may be changed between the SMC4 high group and the SMC4 low group in sarcomas." (PMID 36719264, 2023). "However, the exact role and mechanism of SMC4 in promoting the progression of sarcomas remain unclear." (PMID 36719264, 2023). "SMC4 could be a potential biomarker for prognosis and immune cell infiltrates in sarcoma." (PMID 36719264, 2023). "Moreover, SMC4 was positively connected to immune cell infiltrates in sarcoma." (PMID 36719264, 2023). "Furthermore, IHC was used to explore the expression of SMC4 in sarcoma tissue." (PMID 36719264, 2023). "Previous studies have shown that SMC4 was an active regulator of inflammatory innate response and highly expressed in sarcomas and some other cancers, but it is still unknown whether the elevated expression of SMC4 in tumor tissues is related to the infiltration of immune cells." (PMID 36719264, 2023). "The expression level of SMC4 in sarcoma was detected using ONCOMINE and TIMER datasets, and then used IHC to confirm the elevated expression of SMC4." (PMID 36719264, 2023). "In patients with sarcoma, the relationship between SMC4 and poor OS and RFS indicates that SMC4 is a potential prognostic biomarker for sarcoma." (PMID 36719264, 2023). "It was confirmed that the expression levels of SMC1A, SMC2, SMC3, SMC4, SMC5 and SMC6 in sarcoma were higher than in normal tissues." (PMID 33460400, 2020). "GEPIA was used to investigate the prognostic ability of SMC1, SMC2, SMC3, SMC4, SMC5 and SMC6 expression in sarcoma." (PMID 33460400, 2020). "We concluded that SMC1A, SMC2, SMC3, SMC4, SMC5 and SMC6 were all highly expressed in sarcoma cell lines." (PMID 33460400, 2020). "According to the Cancer Cell Line Encyclopedia (CCLE), SMC1A, SMC2, SMC3, SMC4, SMC5 and SMC6 are also highly expressed in sarcoma cell lines." (PMID 33460400, 2020). "Our results also suggest that SMC1A and SMC2 are potential therapeutic targets for sarcoma, while levels of transcripts of SMC3, SMC4, SMC5 and SMC6 are potential prognostic markers to improve the survival rate and prognostic accuracy of sarcoma." (PMID 33460400, 2020). "Third, no experiments were conducted to confirm the role of SMC4 in the development of sarcoma, and its relationship with the level of immune cell infiltration." (PMID 36719264, 2023). "We found that increased expression of SMC1A, SMC2, SMC3, SMC4, SMC5 and SMC6 might play a significant role in sarcoma tumorigenesis." (PMID 33460400, 2020). "Higher SMC4 expression tended to be associated with poor OS and DFS in sarcoma, but this also failed to achieve significance." (PMID 33460400, 2020). "In contrast, SMC3, SMC4, SMC5, and SMC6 expression had no significant impact on OS or DFS in sarcoma." (PMID 33460400, 2020). "However, only the overexpression of SMC1A and SMC2 was related to the OS of sarcoma patients, whereas SMC3, SMC4, SMC5 and SMC6 had no significant impact on prognosis." (PMID 33460400, 2020).
synovial sarcoma (2 papers, 2020 to 2023). "First, our study results with respect to the role of SMC4 in tumors were based on the data from several databases and we only performed immunohistochemical verification on the expression level of SMC4 in synovial sarcoma." (PMID 36719264, 2023). "This revealed that SMC1A, SMC2, SMC3, SMC4, SMC5 and SMC6 proteins were all more highly expressed in the synovial sarcoma tissues than in corresponding normal tissues." (PMID 33460400, 2020).
Allergy (1 paper, 2021). An allergy is an immune response or reaction to substances that are usually not harmful. "We found that SMC4 and FANCB are independent predictors for survival, and TOP2A, mold/dust allergy and preoperative corticosteroids are independent predictors for the PFI of LGG patients." (PMID 34868977, 2021).
Alzheimer disease (1 paper, 2023). A progressive, neurodegenerative disease characterized by loss of function and death of nerve cells in several areas of the brain leading to loss of cognitive function such as memory and language. "Worth a mention is the downregulation of DDIT3, SMC4, and TENM4 in replicative senescence of human fibroblasts; the upregulation of SMC4 and MCM7 after vitamin C treatment; the upregulation of HOXB3 and TENM4 in Alzheimer’s disease; and the deregulation of DDIT3 and SMC4 in COVID-19 disease." (PMID 36982191, 2023).
autoimmune disease (1 paper, 2023). A disorder resulting from loss of function or tissue destruction of an organ or multiple organs, arising from humoral or cellular immune responses of the individual to their own tissue constituents. "Moreover, SMC4 is also a positive regulator of the inflammatory innate immune response, while An excessive innate immune response not only disrupts the immune balance, leading to autoimmune diseases but also even results in cancer." (PMID 37007153, 2023). "On the other hand, SMC4 is also a positive regulator of the inflammatory innate immune response, while excessive innate immune responses not only disrupt immune homeostasis and may lead to autoimmune diseases, but even cancer." (PMID 37007153, 2023).